LDHA (lactate dehydrogenase A)
Diseases named in the same sentence as LDHA in open-access papers (continued):
Sharing a sentence is not in itself a finding about the gene and the disease.
cancer (continued). "The tyrosine phosphorylation of LDHA is important for NADH/NAD+ redox homeostasis in cancer cells, due to a compensatory increase in mitochondrial respiration in Y10F cells." (PMID 36407005, 2022). "GLUT1, HK2, TGK1, and LDHA are key components of the glycolysis pathway and play key roles in cancer metabolism, suggesting that mTORC1-NEAT1 signaling regulates glucose metabolism." (PMID 35547764, 2022). "FGF signaling also protects from LDHA degradation and deletion of FGFR1 blocks to use lactate as a main energy source and LDHB expression is associated with poor survival in cancer patients." (PMID 36077431, 2022). "LDHA directly converts pyruvate into lactic acid and is highly expressed in a variety of malignant tumors and is closely related to cancer prognosis." (PMID 35669414, 2022). "High-risk genes (C1QTNF6, LDHA, IGF2BP1) resulted in poor clinical outcomes by promoting cancer cell metabolism and proliferation." (PMID 36032673, 2022). "Lactate dehydrogenase A (LDHA), an enzyme that promotes cancer cell invasion and catalyses the conversion of pyruvate to lactate, is highly elevated in several cancers and is closely associated with cancer progression." (PMID 35955595, 2022). "It has been documented that LDHA is upregulated in various human cancers, which promotes glycolytic metabolism and cancer development." (PMID 36418319, 2022). "The oncogene MYC has been shown to upregulate lactate dehydrogenase A (LDHA), an important glycolytic enzyme that is necessary to increase the glycolytic rate and tumorigenic potential of cancer cells." (PMID 35530337, 2022). "Patients with high LDHA levels in tumors also displayed unfavorable pathological parameters, such as advanced cancer grade and shorter overall survival times." (PMID 36307872, 2022). "Increasing evidences have shown that LDHA is upregulated in various cancers, which is related to the clinicopathological characteristics and prognosis of patients and involved in cancer growth." (PMID 35193567, 2022). "FGFR1-mediated metabolic LDHA activation and LDHB deactivation are associated with cancer growth and progression." (PMID 36077431, 2022). "Nevertheless, these results considered altogether confirm the significant contribution of LDHA to cancer development in the esophagus." (PMID 36555705, 2022). "Because cancer cells are known to rapidly adapt and become resistant to anti-cancer therapies, in this study, we modeled the adaptation of cancer cells to LDHA inhibition." (PMID 35982980, 2022). "In a previous study, LDHA silencing induced a decrease in lactic acid concentration, and cancer cell migration was reduced by approximately 40% compared to the control siRNA." (PMID 35193567, 2022). "Suppression of glucose metabolism by targeting LDHA can sensitize cancer cells to cisplatin treatment." (PMID 35832094, 2022). "They regulate the expression of glycolytic enzymes including hexokinase 2 (HK2), pyruvate kinase M2 isoform (PKM2), lactate dehydrogenase A under normoxia and hypoxia, and promote the survival of cancer cells and the growth of cancer tissues." (PMID 35912204, 2022). "The glycolytic shift of cancer cells appears to be the result of FLCN inactivation or dissociation from LDHA." (PMID 35457153, 2022). "In normoxic conditions, physiological cells produce ATP by oxidative phosphorylation, while cancer cells transform pyruvate in lactate through lactate dehydrogenase A (LDHA)." (PMID 35334812, 2022). "To constantly inhibit lactate generation in B16-F10 cells, we constructed B16-F10 cells with LDHA knocked out (B16-F10 Ldha-/- cells) because LDHA is the predominantly enzymatic form of LDH in cancer cells." (PMID 36531060, 2022). "As validated in a number of studies, the LDHA expression is upregulated in cancer cells in contrast to the approximately intact expression levels of LDHB in normal and carcinomatous tissues." (PMID 36518315, 2022).
cancer (continued). "Replacement of endogenous LDHA with an acetylation mimetic mutant leads to a decrease in cancer cell proliferation and migration, indicating the critical role of LDHA acetylation in cell growth control." (PMID 36407005, 2022). "Then, to trace the distribution of LDHA in esophageal normal (n = 6) and cancer tissues (n = 9), paraffin sections were stained by IHC." (PMID 36555705, 2022). "Accordingly, LDHA has become an attractive target for possible pharmacological approaches in cancer therapy." (PMID 36518315, 2022). "Galloflavin, which inhibits LDH, improves cell viability and survival in acute liver failure, suggesting that the LDHA inhibitor plays roles in not only cancer therapy." (PMID 36407005, 2022). "Pyruvate dehydrogenase kinase (PDH- kinase), Hypoxia-inducible factors (HIFs) and Lactate dehydrogenase A (LDHA) enzymes but also mitochondrial malignant cell dysfunction are factors involved in the glycolytic nature of cancer metabolism." (PMID 36568220, 2022). "LDHA has been reported to be overexpressed in cancer cells, and contributes to several oncogenic behaviors, the most relevant of which is maintaining cell survival under nutrient stress." (PMID 36310768, 2022). "Investigation of the potential crosstalk between these posttranslational modifications and their effects on LDHA enzyme function, especially in relation to cancer, would be informative." (PMID 35525866, 2022). "The deregulation of LDHA is observed in many cancers, including prostate, breast, hepatocellular, and gastrointestinal cancers." (PMID 36230479, 2022). "Inhibition of LDHA in cancer cells leads to a decrease in the potential of the mitochondrial membrane and leads to cell death." (PMID 35628385, 2022). "Knockdown of LDHA can inhibit cancer cell proliferation, suggesting that targeting LDHA is a promising strategy to inhibit the growth of malignant tumors." (PMID 36230492, 2022). "For example, the combination of PKM2 activators and LDHA inhibitors significantly reduced cancer growth in a mouse model of pancreatic adenocarcinoma transplantation, suggesting the potential value of multitarget glycolytic inhibitors in combination." (PMID 36230492, 2022). "As the most effective isoform in the family to catalyze pyruvate to lactate, most studies on this family focus on LDHA, and aberrant activation of LDHA has been found to be closely related to diverse cancers." (PMID 36407005, 2022). "AZD.0530 is an Src inhibitor that attenuates lactate dehydrogenase A activity through phosphorylation, thus inhibiting cancer invasion and metastasis." (PMID 38090653, 2022). "In the liver, LDHA is mostly present in the mitochondrial matrix, whereas it is mainly localized in the cytoplasm of cancer cells." (PMID 36518315, 2022). "Future functional studies related to these changes remain necessary to reveal the direct roles played by these changes in the development of LDHA inhibitor resistance and uncover approaches for more effective use of LDHA inhibitors in cancer therapy." (PMID 35982980, 2022). "In many types of cancers, c-Myc is always activated and plays key role in reprogramming glycolytic metabolism by activating its target genes, like GLUT1, HK2, PKM2 and LDHA, and then results in cancer cell proliferation, migration and metastasis." (PMID 35689245, 2022). "LDHA is often up-regulated in invasive cancer cells with a high glycolytic rate and is important for cell proliferation in cancer." (PMID 35897809, 2022). "It has also been reported that LDHA phosphorylation and activation promote cancer cell invasion and metastasis." (PMID 35936690, 2022). "The conversion of pyruvic acid to lactic acid catalyzed by LDHA is required to sustain the increased rates of glycolysis in cancer cells." (PMID 36531060, 2022). "Lactate dehydrogenase A (LDH-A) is a recognized innovative target for cancer therapy and the development of LDH-A inhibitors from bioactive compounds derived from herbs has been gaining interest in drug development." (PMID 36139460, 2022).
cancer (continued). "In cellular metabolism, the formation of lactate from pyruvate is catalyzed by LDHA, which is characteristic of cancer glycolysis." (PMID 36313570, 2022). "The expression of LDHA is increased in cancer cells that prefer glycolytic metabolism, including lymphomas, melanomas, and prostate tumors." (PMID 36551514, 2022). "Among the cancers with increased LDHA, kidney renal clear cell carcinoma (KIRC) is shown to be the top one." (PMID 35637958, 2022). "Low c-Myc inhibits uncontrolled DNA synthesis associated with cancer and thus lowers the expression of PGM, PKM, and LDHA, and eventually downregulates carbon consumption needed to sustain malignancy." (PMID 36364182, 2022). "Several studies have suggested that aberrantly high expression of LDHA in numerous cancers significantly affects the invasion and migration of malignant cells." (PMID 35936690, 2022). "Lactate accumulation mediated by abnormally high expression of LDHA is a common and major feature of cancer metabolism, so targeting LDHA is a safe and effective strategy that has been tested clinically." (PMID 36686771, 2022). "In gastric cancer cells, FOXM1 regulates many cellular processes via LDHA, including stimulation of glycolysis, proliferation, invasion, and migration of cancer cells." (PMID 36551514, 2022). "The lactate dehydrogenase (LDHA), an important enzyme of the glycolysis, catalyzes the generation of lactate, and its high expression has been verified in a myriad of cancers, which is related to malignant progression." (PMID 36033372, 2022). "In cancer cells, LDHA plays an important role in rapid conversion of pyruvate to lactate, minimizing in this way the pyruvate entry into TCA cycle in the mitochondria." (PMID 35433453, 2022). "HIF-1α is an oxygen-sensitive transcription factor that regulates LDHA transcription in human cancers." (PMID 35757505, 2022). "Increased activity of LDHA, increased glycolysis, and increased production of lactate, inhibiting LDHA activity affects cancer cell proliferation." (PMID 36686771, 2022). "LDHA is up regulated in many cancers, resulting in increased catalytic product lactate and poor prognosis." (PMID 36313645, 2022). "LncRNA GLCC1 stabilizes c-Myc through direct interaction with HSP90 chaperon and transactivates target genes such as LDHA, thereby reprograming glycolytic metabolism for cancer cell proliferation." (PMID 36418319, 2022). "In particular, c-MYC and HIF-1α promote the expression of glycolytic enzymes hexokinase 2 (HK2), phosphofructokinase 1 (PFK1), triosephosphate isomerase 1 (TPI1), lactate dehydrogenase A (LDHA) in cancer." (PMID 36313705, 2022). "Recent studies have focused on the regulatory function of lncRNAs in cancer cell glucose metabolism through LDHA." (PMID 36072431, 2022). "We evaluated the gene expression level of LDHA within different molecular or histological subtypes in four cancer types in TCGA publications." (PMID 36072431, 2022). "Direct targeting of glycolysis can be achieved by administering an inhibitor such as NCI-737 to lactate dehydrogenase A (LDHA), the main enzyme responsible for the Warburg effect that has shown promise as an anti-cancer agent in preclinical trials." (PMID 34712243, 2021). "Further and in support of nuclear LDHA enhancement in malignant tumors, this pattern was also reproduced in our GBM TMA tissue microarray." (PMID 33996536, 2021). "Cancer cells with miR-374a overexpression exhibit reduced LDHA levels compared to miR-374a-MUT (rs18407893 at 11p15.4)." (PMID 34208601, 2021). "The co-expression network indicated the crucial role of LDHA in searching for novel targets in drug effect regulation and cancer-related chemotherapy." (PMID 34307169, 2021). "LDHA inhibition by oxamate remarkably increased radiosensitivity in both A549 and H1975 cancer cells, and enhanced ionizing radiation (IR)-induced apoptosis and autophagy, accompanied by cell cycle distribution alternations." (PMID 33902615, 2021).
cancer (continued). "Several important glycolytic regulators including hexokinase 2 (HK2), pyruvate kinase M2 (PKM2), and lactate dehydrogenase A (LDHA), have been proved to be upregulated in the cancer cells." (PMID 33572615, 2021). "Treatment with SU212 inhibited the expression of LDHA, which is an indicator of the Warburg effect due to its role in aerobic glycolysis and lactate production by cancer cells." (PMID 33139797, 2021). "Previous literature has indicated that β-catenin-mediated c-Myc expression upregulates several glycolytic genes, including SLC2A1 (GLUT1) and LDHA, thereby promoting the Warburg effect in cancer cells." (PMID 34575112, 2021). "Third, LDHA inhibits apoptosis by protecting the cancer cells from ROS damage and promoting the expression of antiapoptotic proteins." (PMID 34540667, 2021). "Second, LDHA is involved in cancer invasion and CSC phenotype through the acidic microenvironment maintained by lactate output." (PMID 34540667, 2021). "A recent study sheds light on the role of LDHA in the development of anoikis, which leads to apoptosis in cancer cells." (PMID 34604067, 2021). "As we know, LDHA inhibition drives cancer cells metabolism from glycolysis to mitochondrial respiration, which results in enhanced oxygen consumption and increased mitochondrial ROS production." (PMID 33902615, 2021). "Despite carbohydrate-restricted diets demonstrated remarkable benefits in cancer patients 83, targeting glycolytic enzymes such as LDHA had limited success." (PMID 34158867, 2021). "Previous studies have shown an LDHA-dependence on cancer cell proliferation under hypoxic environment conditions." (PMID 33714987, 2021). "Lactate dehydrogenase A (LDHA) is a key glycolytic enzyme, a hallmark of aggressive cancers and is believed to be the major enzyme responsible for pyruvate to lactate conversion." (PMID 34066944, 2021). "Specifically, inhibitors with targets related to glycolysis including hexokinase 2 (HK2) and lactate dehydrogenase A (LDHA) are useful in selectively killing cancer cells." (PMID 35004842, 2021). "As previously reported, inhibition of LDHA increases the ROS and consequently suppressed the growth of cancer cells." (PMID 34065602, 2021). "Using GESA analysis, LDHA expression is positively related to enhanced glucose intake and glycolysis, which promote cancer cell growth and progression." (PMID 33902615, 2021). "Knockdown studies of both PKM2 and LDHA have been shown to reduce ATP production, inhibit cell growth, decrease invasiveness, and induce oxidative stress and radiosensitivity in cancer cells." (PMID 34367959, 2021). "Nevertheless, in GBM cells, LDHA as an oncogene affects cancer cell movement in A172 and U87MG cells." (PMID 34209254, 2021). "Several glycolysis-related proteins, for example, GLUT1, HK2, and LDHA, are often upregulated in several types of cancer, which are related to the Warburg effect and cancer progression." (PMID 34575112, 2021). "LDHA is a rate-limiting enzyme of glycolysis that catalyses the production of lactate, which is relevant to malignant biological behaviours in diverse cancers." (PMID 34743698, 2021). "Many aerobic glycolytic cancers have increased expression of LDHA, which preferentially converts pyruvate into lactate and thereby increases lactate secretion but decreases pyruvate secretion." (PMID 33230593, 2021). "LDHA is highly expressed in cancer cells and regarded as a biomarker of multiple malignant cancers, including lymphoma, prostate cancer, renal cell carcinoma, melanoma as well as PTC." (PMID 34404767, 2021). "To confirm the role of the AMPK/mTOR signaling in regulating LDHA‐induced cancer cell progression, we then pharmacologically inhibited AMPK expression with 20 μM Compound C, a selective and cell‐permeable AMPK inhibitor, in LDHA‐SH cells." (PMID 34185423, 2021). "High levels of LDHA expression serves as a prognostic indicator in patients with different type of cancers." (PMID 34926609, 2021).
cancer (continued). "Positive LDHA immunostaining was observed in all benign tumors and hyperplastic samples, and in the majority of malignant tumors (95%) and CANT (81%) samples." (PMID 33996536, 2021). "The enzyme lactate dehydrogenase A (LDHA) which converts pyruvate into lactate, not only plays a central role in cancer cell aerobic glycolytic capacity but exerts similar function in T-cell function through PI3K signaling." (PMID 35070990, 2021). "In turn, the LDHA-dependent lactate increases proliferation of hypoxic cancer cells as well as migration and invasion." (PMID 33714987, 2021). "Enhanced expression of LDHA has been demonstrated to promote the sustained proliferation of cancer cells, and to contribute in promoting the epithelial to mesenchymal transition, angiogenesis, cell motility, invasion and migration." (PMID 34205977, 2021). "Functionally, exposure of L‐lactate to berberine‐treated cancer cells attenuated the growth and invasion suppression by berberine, suggesting the restoration of LDHA attenuated the suppressive effect of berberine on PAAD." (PMID 34185423, 2021). "HK2 and LDHA are the glycolytic pathway genes playing crucial roles in the Warburg effect in cancer cells and their inhibition by DOX and apigenin co-administration possibly hamper the growth and proliferation of cancer cells." (PMID 34715860, 2021). "Since the LDH A subunit (LDHA) is upregulated in a range of different cancers and LDHA-targeting therapeutics are available, it is important to study this gene’s impact on HCC in greater detail." (PMID 33747521, 2021). "Intriguingly, we observed an increase in glycolytic capacity and reserve following TGFβ2 treatment which was accompanied by an increased expression of glycolytic enzymes, PFKFB3, PKM2 and LDHA, linked to EMT in cancer metastasis models." (PMID 33946753, 2021). "Of note, although inhibition of LDHA mainly induces cell apoptosis by generating ROS, different responses to glycolysis inhibition were observed in different cancer cells." (PMID 33902615, 2021). "Conversion of glucose carbon to lactate by the lactate dehydrogenase (LDHA) enzyme is a classic signature of cancer metabolism." (PMID 33762012, 2021). "LDHA is highly expressed in many types of cancers and considered as the key player of aerobic glycolysis." (PMID 33792181, 2021). "LDHA executes the final step of glycolysis, and the resultant lactate production leads to a relatively low pH allowing cancer cells to survive immune evasion by diminishing T and NK cell activation." (PMID 34452627, 2021). "In contrast to CAIX, LDHA is expressed in normal tissues and in many types of cancers, hypoxia-induced its expression." (PMID 33996536, 2021). "In this study, we used shRNA to inhibit LDHA activity to make cancer cells sensitive to anoikis induction." (PMID 34604067, 2021). "The enzyme activity of LDHA thus is considered as a therapeutic target for the suppression of tumor growth and distant metastasis in different cancer types." (PMID 34207284, 2021). "Another study also showed that the inhibition of lactate dehydrogenase A (LDHA) prevented the Warburg effect and forced cancer cells to revert to oxidative phosphorylation in order to re-oxidize NADH and produce ATP." (PMID 34638609, 2021). "Lactate dehydrogenase A (LDHA) is an important glycolytic enzyme that promotes glycolysis and plays a crucial role in cancer cell invasion and immune infiltration." (PMID 34307169, 2021). "MB, CAIX, and LDHA expression in tissue microarrays of benign tumors, multiple organ tumors, hyperplasia, and cancer adjacent-normal tissue." (PMID 33996536, 2021). "The irradiated FaDu cancer cells showed significantly decreased expression levels of LDHA and LDHB (p = 0.049 and 0.001, respectively)." (PMID 34436459, 2021). "Lactate dehydrogenase A (LDHA) is an important glycolytic molecule that promotes glycolysis by catalyzing the interconversion of pyruvate and lactate, and promotes cancer cell invasion." (PMID 34307169, 2021).